G6PD (glucose-6-phosphate dehydrogenase)
Description:
Catalyzes the rate-limiting step of the oxidative pentose-phosphate pathway, which represents a route for the dissimilation of carbohydrates besides glycolysis. The main function of this enzyme is to provide reducing power (NADPH) and pentose phosphates for fatty acid and nucleic acid synthesis. Also catalyzes the conversion of NAADPH, which is produced by enzymes such as DUOX1, DUOX2 and NOX5 from NAADP and promotes Ca(2+) signaling during T cell activation, back to NAADP.
Synonyms: G6PD1; CNSHA1
Tractability: Small molecule: a structure with a bound ligand is known; a high-quality ligand is known; it has a high-quality binding pocket; it belongs to a druggable protein family. Antibody: UniProt places it where antibodies can reach, with high confidence. PROTAC: ubiquitination databases record sites on it; its protein half-life has been measured; a small molecule that binds it is known.
Target class: Enzyme; Oxidoreductase
Safety:
Unwanted effects reported when the protein is acted on. In parentheses: how it was acted on, where the effect was seen, and who reports it.
N/A, Cyanosis occurs (inhibition; source: AOP-Wiki)
hemolysis (source: ClinPGx)
hemolysis and severe/unsafe hemoglobin decreases (source: ClinPGx)
hemolysis or hemolytic anemia (source: ClinPGx)
hemolytic anemia (source: ClinPGx)
may not respond to treatment for methemoglobinemia (source: ClinPGx)
methemoglobinemia and/or hemolysis (source: ClinPGx)
moderate anemia (source: ClinPGx)
pulmonary damage (source: ClinPGx)
requiring a blood transfusion (source: ClinPGx)
respond to treatment for methemoglobinemia (source: ClinPGx)
survival of red blood cells (source: ClinPGx)
unknown hemolysis (source: ClinPGx)
unknown rate of red blood cell survival (source: ClinPGx)
varying degree of G6PD deficient red blood cells (source: ClinPGx)
varying degree of G6PD deficient red blood cells and an unknown hemolysis (source: ClinPGx)
varying degree of G6PD deficient red blood cells and an unknown hemolytic anemia (source: ClinPGx)
varying degree of G6PD deficient red blood cells and unknown hemolytic anemia (source: ClinPGx)
Gene: Protein-coding gene on chromosome X (154,517,825 to 154,547,584, reverse strand). Ensembl gene ENSG00000160211.
Subcellular location: Cytoplasm, cytosol; Membrane
Subcellular location (Human Protein Atlas): Cytosol; Centriolar satellite
Pathways (Reactome):
Cellular responses to stimuli: NFE2L2 regulates pentose phosphate pathway genes
Metabolism: Pentose phosphate pathway
Gene Ontology:
Molecular function: D-glucose binding; glucose-6-phosphate dehydrogenase activity; identical protein binding; NADP binding; protein binding; protein homodimerization activity; carbohydrate binding; oxidoreductase activity, acting on CH-OH group of donors
Biological process: cellular response to oxidative stress; cholesterol biosynthetic process; erythrocyte maturation; glucose 6-phosphate metabolic process; glutathione metabolic process; NADP+ metabolic process; pentose biosynthetic process; pentose-phosphate shunt; pentose-phosphate shunt, oxidative branch; ribose phosphate biosynthetic process; substantia nigra development; lipid metabolic process; glucose metabolic process; negative regulation of cell growth involved in cardiac muscle cell development; negative regulation of reactive oxygen species metabolic process; positive regulation of calcium ion transmembrane transport via high voltage-gated calcium channel; regulation of neuron apoptotic process; response to ethanol; response to food; response to iron(III) ion
Cellular component: cytoplasm; cytoplasmic side of plasma membrane; cytosol; extracellular exosome; membrane
Gene-disease validity (ClinGen):
ClinGen rates the evidence that G6PD causes each of these diseases.
anemia, nonspherocytic hemolytic, due to G6PD deficiency (X-linked): Definitive. Any nonspherocytic hemolytic anemia in which the cause of the disease is a variation in the G6PD gene resulting in severely decreased activity levels of the enzyme glucose-6-phosphate dehydrogenase.
G6PD deficiency (X-linked): Definitive. An X-linked genetic condition caused by alterations in the gene G6PD that result in moderately to severely decreased activity levels of the enzyme glucose-6-phosphate dehydrogenase.
Homologues: Orthologues: chimpanzee G6PD (99% identical), mouse G6pdx (94% identical), rat G6pd (94% identical), guinea pig G6PD (93% identical), macaque G6PD (93% identical), dog G6PD (92% identical), rabbit G6PD (90% identical), mouse G6pd2 (87% identical), pig G6PD (83% identical), tropical clawed frog g6pd (77% identical), zebrafish g6pd (76% identical), Drosophila melanogaster Zw (64% identical), and 1 more. Paralogues in human: H6PD (31% identical).
Diseases named in the same sentence as G6PD in open-access papers:
G6PD is named in the same sentence as 495 diseases in open-access papers, as found by Europe PMC text mining. Sharing a sentence is not in itself a finding about the gene and the disease. The quoted sentences say what the papers report.
G6PD deficiency (681 papers, 2005 to 2026). "Glucose-6-phosphate dehydrogenase (G6PD) deficiency was also commonly reported, with prevalence reaching up to 60% in some populations." (PMID 41951986, 2026). "Glucose-6-phosphate dehydrogenase (G6PD) deficiency, the most common erythrocyte enzymatic disorder, predisposes patients to oxidative stress-induced acute hemolysis." (PMID 41647927, 2026). "Screening for G6PD deficiency was considered in our case before starting dapsone therapy as it can cause severe hemolysis in G6PD deficient individual which can be life threatening." (PMID 41473884, 2026). "A 23-month-old, 8-kg boy with known glucose-6-phosphate dehydrogenase (G6PD) deficiency presented with a coin lodged in the upper esophagus and required urgent rigid esophagoscopy under general anesthesia." (PMID 42281694, 2026). "Glucose-6-phosphate dehydrogenase (G6PD) deficiency is an X-linked disorder that increases red blood cell susceptibility to oxidative damage." (PMID 41647324, 2026). "Pegloticase is an effective therapy for refractory gout but carries a risk of oxidative hemolysis in patients with glucose-6-phosphate dehydrogenase (G6PD) deficiency." (PMID 42017087, 2026). "Monitoring is recommended in patients with renal disease, a history of nephrolithiasis, or glucose-6-phosphate dehydrogenase (G6PD) deficiency." (PMID 41465314, 2025). "Upon analyzing all exons of G6PD in the 80 patients with G6PD deficiency, 17 mutation types were detected with a 100% detection rate." (PMID 40313950, 2025). "The most frequently observed condition was glucose-6-phosphate dehydrogenase (G6PD) deficiency, followed by GJB2-related hearing loss." (PMID 41329681, 2025). "None of the included individuals carried the Mediterranean-type G6PD B– genotype, which is often associated with severe G6PD deficiency." (PMID 41452897, 2025). "Glucose-6-phosphate dehydrogenase (G6PD) deficiency also shows dramatic RBC-EV release, one study found circulating EVs (≈45% RBC-derived) ∼4–10-fold higher in G6PD-deficient versus healthy blood and increasing with disease severity." (PMID 40901521, 2025). "We also examined two genes in more depth, DUSP9, which is associated with type 2 diabetes, and G6PD, which is associated with type 2 diabetes and is causal for G6PD deficiency." (PMID 41286645, 2025). "GS, when combined with conditions like thalassaemia, glucose-6-phosphate dehydrogenase (G6PD) deficiency, spherocytosis, and ALL can increase the risk of severe hyperbilirubinemia." (PMID 39996891, 2025). "G6PD deficiency is an X-linked disorder caused by pathogenic variants in the G6PD gene, leading to variable enzyme activity levels." (PMID 41464329, 2025). "Despite the overlap between dengue and G6PD deficiency, relatively few studies have investigated the genetic spectrum of G6PD variants in Thai dengue patients or explored trends in hemoglobin levels in relation to genotype." (PMID 40966243, 2025). "G6PD deficiency has a genetic etiology introduced by inherited X-linked aberrant mutations in the G6PD gene, leading to reduced activity or stability of the corresponding enzyme." (PMID 40799291, 2025). "Glucose-6-phosphate dehydrogenase (G6PD) deficiency has a distinct regional and ethnic heterogeneity in distribution, and information on the molecular characteristics of G6PD deficiencies in the Heze area, Shandong Province, China, is limited." (PMID 40313950, 2025). "Hereditary G6PD deficiency is caused by sequence variations in G6PD, which is highly polymorphic with over 230 variants identified, due to its association with malaria resistance." (PMID 40307426, 2025). "This study presents a comprehensive assessment of G6PD deficiency among adult dengue patients in Thailand, offering new insights into both its prevalence and molecular spectrum of G6PD variants." (PMID 40966243, 2025).
G6PD deficiency (continued). "For instance, G6PD plays a central role in redox balance and cellular protection against oxidative stress and G6PD deficiency can cause acute hemolytic anemia in humans." (PMID 41465102, 2025). "Glucose-6-phosphate dehydrogenase (G6PD) deficiency is an important predisposing factor for both hemolytic anemia and methemoglobinemia." (PMID 41552137, 2025). "Based on the enzyme activity, G6PD c.479G>A/p.S160N and c.404A>T/p.N135I are potentially pathogenic and cause G6PD deficiency through different mechanisms." (PMID 40313950, 2025). "Treatment with dapsone at 1.5 mg/kg/d was started after excluding glucose-6-phosphate dehydrogenase (G6PD) deficiency." (PMID 40995939, 2025). "In this study, 19 G6PD variants associated with G6PD deficiency were identified by using next-generation sequencing." (PMID 40447697, 2025). "Glucose-6-phosphate dehydrogenase (G6PD) deficiency is the most common red-cell enzymopathy worldwide, yet symptomatic disease in women is uncommon because of its X-linked inheritance." (PMID 41216053, 2025). "G6PD deficiency was identified in 24 individuals (10.4%), while G6PD mutations were detected in 111 patients (48.1%)." (PMID 40966243, 2025). "The World Health Organization2 recommends routine G6PD screening of newborns in areas where the prevalence of G6PD deficiency is as high as 3% – 5%, or more." (PMID 41200155, 2025). "Significant risk factors include advanced age, glucose-6-phosphate dehydrogenase (G6PD) deficiency, diabetes mellitus, and male sex." (PMID 41019081, 2025). "It requires prior testing for G6PD deficiency, because treating G6PD‐deficient patients with tafenoquine can lead to haemolysis and potentially fatal outcomes." (PMID 40990168, 2025). "The patient was treated with rasburicase for hyperuricemia, from which she developed methemoglobinemia, a rare complication in patients with glucose-6-phosphate dehydrogenase (G6PD) deficiency." (PMID 40161169, 2025). "Glucose-6-phosphate dehydrogenase (G6PD) deficiency is an inherited enzymopathy common in malaria-endemic regions, with an estimated prevalence of 13.6% in Thailand." (PMID 40274286, 2025). "Vicine and convicine, natural pyrimidine glycosides, are particularly problematic as they can induce favism (hemolytic anaemia) in individuals with glucose-6-phosphate dehydrogenase (G6PD) deficiency." (PMID 40363814, 2025). "Mutations in G6PD cause glucose-6-phosphate-dehydrogenase deficiency, which can lead to hemolytic anemia in the presence of oxidative stress." (PMID 41286645, 2025). "Glucose-6-phosphate dehydrogenase (G6PD) deficiency is the most common inherited enzymopathy worldwide, affecting approximately 400 million people." (PMID 41464329, 2025). "This means alerting pregnant women and their families to gain more knowledge about the G6PD deficiency disease to provide early screening for the G6PD gene for pregnant women and fetuses to reduce this disease burden in Vietnam." (PMID 40447697, 2025). "Primaquine is underused because of concerns over oxidant hemolysis in glucose-6-phosphate dehydrogenase (G6PD) deficiency." (PMID 39992119, 2025). "The most prevalent metabolic condition of red blood cells, glucose-6-phosphate dehydrogenase (G6PD) deficiency, affects around 35 million people globally." (PMID 40367898, 2025). "Molecular detection of G6PD deficiency can help to identify specific G6PD mutation types, and the commonly used detection methods include whole gene, exon, and common site detection." (PMID 40313950, 2025). "Plasmodium vivax-infected patients should be screened and assessed for the level of G6PD enzymatic activity before prescribing primaquine or adjusting primaquine dose in individuals with mild to moderate G6PD deficiency." (PMID 41452897, 2025). "It is important to note that methylene blue is contraindicated in individuals with glucose-6-phosphate dehydrogenase (G6PD) deficiency due to the risk of hemolysis." (PMID 40755623, 2025).
G6PD deficiency (continued). "Glucose-6-phosphate dehydrogenase (G6PD) deficiency remains a significant global health burden, particularly in malaria-endemic regions." (PMID 40486677, 2025). "Glucose-6-phosphate dehydrogenase (G6PD) deficiency is a widespread enzymopathy affecting approximately 500 million individuals that represents a significant global health issue." (PMID 40943386, 2025). "Glucose-6-phosphate dehydrogenase (G6PD) deficiency is caused by mutations in the G6PD gene, resulting in varying degrees of enzyme deficiency and changes in protein expression, leading to various clinical subtypes." (PMID 39318598, 2024). "Comparison of ROC curves of G6PD activity in predicting G6PD deficiency between different seasons of FuYang." (PMID 38496015, 2024). "Hemolytic anemia is another potential hematologic toxicity associated with sulfasalazine use, particularly in patients with glucose-6-phosphate dehydrogenase (G6PD) deficiency." (PMID 39329122, 2024). "The relationship between diabetic ketoacidosis (DKA), glucose-6-phosphate dehydrogenase (G6PD) deficiency, and methemoglobinemia is complex and multifaceted." (PMID 38966448, 2024). "Glucose-6-phosphate dehydrogenase (G6PD) deficiency is an X-linked recessive Mendelian genetic disorder characterized by neonatal jaundice and hemolytic anemia, affecting more than 400 million people worldwide." (PMID 38496015, 2024). "More severe G6PD deficiency variants are associated with greater drug-induced haemolysis as a broader erythrocyte age range is G6PD-depleted." (PMID 38319064, 2024). "The association of the G6PD rs72554664-T allelic variant with a higher risk of T2DM highlights the importance of sex-specific mechanisms in the interplay between G6PD deficiency and T2DM." (PMID 38834682, 2024). "G6PD deficiency is a hereditary disorder, with the highest prevalence of G6PD-deficient individuals in malaria-endemic regions." (PMID 38741094, 2024). "As for chronic diseases, 22 (7.8%) had glucose-6-phosphate dehydrogenase (G6PD) deficiency, eight (2.8%) had hypothyroidism, and two (0.7%) had autism spectrum disorder (ASD), two (0.7%) had celiac disease, and two (0.7%) had sickle cell disease (SCD)." (PMID 39845243, 2024). "vivax/mixed infections were reported, 1,282 patients underwent G6PD deficiency testing, and 959 patients received radical cure, achieving 29.6% radical cure coverage among all P. vivax/mixed cases and 98.8% coverage among G6PD normal patients." (PMID 38395925, 2024). "The main adverse effect of primaquine, and the other 8-aminoquinoline antimalarials, is dose-dependent oxidant haemolysis in individuals with glucose-6-phosphate dehydrogenase (G6PD) deficiency." (PMID 38319064, 2024). "The 8-aminoquinolines—primaquine and tafenoquine—are the only available antimalarials that eliminate hypnozoites and thus prevent relapses, but they can cause severe haemolysis in individuals with glucose-6-phosphate dehydrogenase (G6PD) deficiency." (PMID 37748496, 2024). "The frequency of G6PD deficiency was reported to still be high in southern Vietnam (8.7% in ethnic Kinh and 14% in ethnic S’tieng), with the most common variant called G6PD Viangchan25." (PMID 38553482, 2024). "Glucose-6-phosphate dehydrogenase (G6PD) deficiency is the most prevalent human enzyme disorder, affecting more than 400 million people, globally, with an estimated prevalence of 4.9%." (PMID 39436963, 2024). "Patient 1 (P1) was a two-month-old infant weighing 4 kg with glucose-6-phosphate dehydrogenase (G6PD) deficiency and Patient 2 (P2) was a toddler aged one year, nine months weighing 9 kg." (PMID 38314387, 2024). "Primaquine and tafenoquine can cause acute haemolytic anaemia in individuals with glucose-6-phosphate dehydrogenase (G6PD) deficiency; severe haemolysis can lead to anaemia, kidney damage, and even death." (PMID 38741094, 2024).